TNF (tumor necrosis factor)
Diseases named in the same sentence as TNF in open-access papers (continued):
Sharing a sentence is not in itself a finding about the gene and the disease.
metastatic melanoma (continued). "Clinical use of L19IL2 and L19TNF, the recombinant fusion protein of recombinant monoclonal antibody (L19) with the human recombinant interleukin-2 (IL-2) or the human tumor necrosis factor-alpha in patients suffering from metastatic melanoma is ongoing (ClinicalTrials.gov Identifier: NCT02076633)." (PMID 32422889, 2020). "TNF is used for localized treatment of metastatic melanomas and other irresectable tumors." (PMID 22536907, 2012). "Furthermore, PD-1 blockade on IFN-γ– and TNF-producing NY-ESO-1-specific CD8+ T cells isolated from peripheral blood mononuclear cells belonging to patients suffering from metastatic melanoma increases the number of these cells and ameliorates the therapeutic process of these patients." (PMID 32902664, 2021). "For example, in a cohort of metastatic melanoma patients treated with CTLA4 and PD-1 blockade, a deep immune analysis of tumor samples found that TNF was markedly upregulated after PD-1 treatment." (PMID 36865537, 2023). "As selective MAPKi were reported to promote T and NK cell infiltration into human metastatic melanoma, it is feasible that IFN-γ- and TNF-producing T and NK cells can modulate TNFR2 expression by and induce MAPKi resistance in BRAFV600E+ metastatic melanomas." (PMID 35879777, 2022). "We detected upregulated production of TNFα and IL-10 by WM1617 metastatic melanoma cell-line-educated-moDCs." (PMID 36194602, 2022). "The biological activity of 70% ~ 95% of the total TNF activity exerted by TNF-α and previous studies have suggested that TNF-α can be used to treat soft tissue sarcomas and metastatic melanoma." (PMID 32552897, 2020). "Like TNF-alpha, IL2 is also added exogenously to treat multiple cancer types including metastatic melanoma and superficial bladder tumors." (PMID 22536907, 2012). "L19-IL2 is an immunocytokine featuring the L19 antibody fused to the cytokine IL2 payload, which is currently being investigated with encouraging results for the treatment of metastatic melanoma in phase II and phase III clinical trials, in combination with targeted TNF." (PMID 33110477, 2020). "In contrast to IL-6 production, treatment with tumor cell-derived supernatants generally did not modify the TNFα secretion by moDCs, but the supernatant of WM1617 metastatic melanoma cell line induced significantly increased TNFα production." (PMID 36194602, 2022).
myositis (37 papers, 2012 to 2025). "We clarify that while TNF inhibitors have been associated with myositis onset or exacerbation, this remains an association rather than definitive causation." (PMID 40861474, 2025). "Muscle inflammation (myositis) is a condition which can be caused by several inflammatory myopathies, in which the TNF-alpha system is involved, as well by muscle stress." (PMID 29183282, 2017). "The association between HLA, TNFα polymorphisms and genetic risk for the pathogenesis of myositis has been reported in subjects with polimyositis, dematomyosistis or myositis overlapping with other connective diseases." (PMID 24204948, 2013). "However, TNF inhibition has paradoxically been linked to new-onset or exacerbation of myositis in predisposed patients." (PMID 40861474, 2025). "The pathogenic role of TNF-α in myositis muscle was not completely understood; however, it has been hypothesized to attract immune cells by enhancing transendothelial cell trafficking in affected muscle." (PMID 23758833, 2013). "Importantly, these interactive cellular networks culminate in a TH1 driven, pro-inflammatory cascade (marked by upregulation of genes encoding the TH1-associated cytokines IFNγ, TNFα, and IL-1β) that steers the disease process away from fibrosis and defines the myositis phenotype in WT mice." (PMID 37809058, 2023). "Similar elevations of cytokines associated with type 1 inflammation, including CXCL9, CXCL10, IFN-γ, IL-12, and TNF have been demonstrated at the protein level in serum of IBM patients versus non-myositis controls." (PMID 40034760, 2025). "TNFα plays a key role in mediating chronic inflammation, cellular infiltration, and tissue remodeling, including fibrosis and myositis." (PMID 41026274, 2025). "We found higher serum levels of IL-10, IL-6, CXCL8, IL-1β, IL-33, IFN-γ, TNF-α, IL-23, and IL-17A in myositis patients compared to the HSs." (PMID 39456842, 2024). "There are assumptions that myotoxic cytokines, such as tumor necrosis factor α (TNFα) and interferon-alpha (IFNα), produced during dengue infection are involved in myositis." (PMID 39026342, 2024). "Myositis patients present a strong Th1 response, with an increased expression of IFNγ, IL-1β and TNFα." (PMID 37726262, 2023). "At time of recommendation consensus forming there was insufficient evidence to recommend anti-TNF-α therapy for treatment of myositis." (PMID 35355064, 2022). "For decades the overexpression of Th1- associated cytokines (TNF-α, IFN-γ and IL-12) in the areas of inflammation in skin and muscle in IIM pointed to Th1 as the primary pathway for inflammation in myositis." (PMID 31429786, 2019). "This demonstrates that in myositis both the muscular system and the nervous system are affected by TNF-alpha." (PMID 29183282, 2017). "Infliximab, an anti-TNF-α medication, has also shown considerable potential for juvenile and adult myositis." (PMID 28610606, 2017). "The functional importance of TNF-alpha in the situation with myositis in response to muscle overuse is completely unclear." (PMID 29183282, 2017). "The findings thus suggest that the overuse model leads to a marked involvement of TNF-alpha in the developing myositis process." (PMID 29183282, 2017). "The findings suggest that there is a pronounced involvement of TNF-alpha in the developing myositis process." (PMID 29183282, 2017). "Our study will deepen the knowledge of the importance of TNF-alpha in the processes that occur in the myositis process in response to marked muscle overuse." (PMID 29183282, 2017). "In a rabbit model leading to muscle inflammation due to overuse, we noted involvement of TNF-alpha in the myositis process." (PMID 29183282, 2017). "It is on the whole obvious that the experience of anti-TNF treatments is very limited for myositis and that more research is needed in order to clarify the effects of this type of treatment in the condition." (PMID 29183282, 2017).
myositis (continued). "Additional patient data included: Disease Activity Scores (DAS), Childhood Myositis Assessment Scale (CMAS), myositis specific antibodies (MSA), and the TNFα-308 promoter region A/G polymorphism." (PMID 27894310, 2016). "Together, these results indicate that the expression of the IL-15/IL-15Rα complex protein by skeletal muscle cells was undetectable under steady state conditions, while induced by TNF-α, IFN-γ, or IFN-α that associates with Th1 response in myositis." (PMID 26417430, 2015). "Increased colon width, inflammatory infiltration, myositis, periganglionitis, ganglionitis, pro-inflammatory cytokines (e.g., TNF-α, INF-γ, IL-2, IL-17, IL-6), and intestinal amastigote nests were more pronounced in high parasite load-bearing animals." (PMID 25889515, 2015). "Interferon alpha (IFN-α), interferon gamma (IFN-γ), tumor necrosis factor alpha (TNF-α), and IL-1α/β are up-regulated in the muscle of myositis patients, which is implicated in the mediation of Th1 and pro-inflammatory responses." (PMID 26417430, 2015). "We have also ourselves noted that there is an enhanced expression of TNF-alpha in the myositis process in the model used in this study and it was concluded that tachykinin (SP) can be involved in its upregulation." (PMID 24725470, 2014). "The etiology of these diseases includes TNF-α signaling, and there is an epidemiological linkage between myositis and several different cancers." (PMID 25163878, 2014). "The most predominantly reported cytokines in myositis include pro-inflammatory cytokines such as IL-1α, IL-1β, TNF-α and transforming growth factor (TGF)-β." (PMID 23758833, 2013). "The significant peak of serum TNFα seen in mice correlated with the second period of hypophagia, occurring during nurse cell development and myositis, and strongly supports this notion." (PMID 23349631, 2013). "To test the function of increased TNFα during myositis we infected p55/p75−/− mice, which lack functional TNFα receptors, and assessed if TNFα was responsible for hypophagia during T. spiralis infection." (PMID 23349631, 2013). "Further studies are therefore required to ascertain the cellular source of TNFα which drives the hypophagia during T. spiralis induced myositis." (PMID 23349631, 2013). "The importance of TNFα in myositis development has been recently confirmed and highlighted in an animal model." (PMID 24204948, 2013). "Using a newly established rabbit model of myositis development, a marked TNF-alpha expression has here been shown for the cells of the inflammatory infiltrates within damaged muscle." (PMID 22505941, 2012). "TNF-alpha immunoreactions in inflammatory cells invading muscles affected by myositis have previously only been documented in biopsies from patients with inflammatory myopathies and in muscle of mice in response to crush-injury." (PMID 22505941, 2012). "IL-1, IL-6, MCP-1, as well as TNFα, are increased in myositis muscle tissues and contribute to disease pathogenesis." (PMID 22577940, 2012). "The aim was to investigate the patterns of TNF-alpha expression in the developing myositis and to evaluate the usefulness of this myositis model for further TNF-alpha research." (PMID 22505941, 2012). "Reactions for TNF-alpha mRNA were revealed for white blood cells of the inflammatory infiltrates in the myositis specimens." (PMID 22505941, 2012). "The main finding was that cells in the inflammatory infiltrates in the myositis muscles were found to express TNF-alpha at both at the mRNA and protein levels." (PMID 22505941, 2012). "Remarkably little data is available on the role of TNF-alpha in situations where there is a pronounced infiltration of inflammatory cells in the muscle tissue, that is, myositis." (PMID 22505941, 2012). "We have taken advantage of this model in order to examine the TNF-system during myositis development." (PMID 22505941, 2012).
myositis (continued). "The current model can be used for further studies on the importance of TNF-alpha in the development of myositis and to document the expression patterns of other cytokines and signal substances in this condition." (PMID 22505941, 2012). "The model can be used in further studies evaluating the importance of TNF-alpha in developing myositis." (PMID 22505941, 2012). "Data addressing a possible TNF-alpha production by inflammatory cells in myositis comes almost entirely from studies of patients affected by a group of diseases known as “idiopathic inflammatory myopathies” (inflammatory myopathies)." (PMID 22505941, 2012). "Pronounced TNF-alpha immunoreactions were observed in cells of the inflammatory infiltrates in all subgroups in the myositis group." (PMID 22505941, 2012). "In any case, the model will, as it is currently used, provide the opportunity to evaluate the effects of interference with TNF-alpha actions in myositis development." (PMID 22505941, 2012). "Animal models are needed to advance our understanding of the disease mechanisms of TNF-alpha that are involved in myositis." (PMID 22505941, 2012). "Moreover, an anti-inflammatory effect was demonstrated in myositis murine model, shown by reduced interleukin 6 (IL-6) and tumor necrosis factor α (TNF-α) mRNA expression." (PMID 40943287, 2025). "TNF‐α gene expression has, for instance, been detected in the sarcopenic skeletal muscle of older individuals, and co‐localized to type I muscle fibres and in myositis patient biopsies." (PMID 36426551, 2022). "Excessive production of TNF-α may play a role in the pathogenesis of myositis, and therefore may lead to a therapeutic role for TNF-α inhibitors, such as infliximab or etanercept, in the treatment of IIM." (PMID 35457124, 2022). "One possibility is that TNF-alpha may play an important role in the pathogenesis of the muscle destruction that occurs in myositis." (PMID 29183282, 2017). "TNF-alpha is suggested to be involved in muscle damage and muscle inflammation (myositis)." (PMID 29183282, 2017). "In order to evaluate whether TNF-alpha is involved in the myositis that occurs in response to muscle overuse, the aim was to examine the expression patterns of TNF receptors in this condition." (PMID 29183282, 2017). "The high levels of tumor necrosis factor (TNF), interferon (IFN)-γ, and interleukin (IL)-12 observed in the blood and muscle tissues of patients with various types of myositis have implicated the T helper type 1 (Th1) response as a key mediator of the pathogenesis of these diseases." (PMID 29259687, 2016). "Importantly, we have also identified the second phase of hypophagia during the period of nurse cell formation to be mediated by a separate myositis-induced immune mechanism, fully dependent on the actions of TNFα." (PMID 23349631, 2013). "Results of in vitro studies suggest that targeting TNF-alpha might be worthwhile in myositis and studies on dystrophic mdx mice subjected to wheel exercise indicate that TNF blockade can reduce myofiber necrosis." (PMID 22505941, 2012). "With this as a basis, studies on TNF-alpha in myositis were performed." (PMID 22505941, 2012). "Thus, in combination with this previous work, our results imply that TNF-alpha is intimately involved in the inflammatory process in myositis." (PMID 22505941, 2012). "Cultured human myoblasts from patients with myositis constitutively produce a low level of cytoplasmic and secreted IL-15, which was also observed in healthy controls; however, mRNA and protein production was increased in DM patients by stimulation with IL-1α, IL-1β, TNF-α, or IFN-γ." (PMID 30766892, 2019). "It is possible that TNF-alpha derived from infiltrated white blood cells, which are likely to be macrophages, may play an important role in the development of the myositis, as was suggested for TNF-alpha in the myositis process that was triggered by alphavirus infection in mice." (PMID 29183282, 2017).
myositis (continued). "As there was a distinct expression for both TNF receptors in the nerve fascicles bilaterally in experimental animals, it is logical to ask the question whether TNF-alpha can be involved in spreading the myositis process to the contralateral side via the nervous system." (PMID 29183282, 2017). "It is actually suggested that TNF-alpha may be a target for myositis development." (PMID 29183282, 2017). "Early non-significant increases in systemic TNFα were seen as early as day 8 post-infection; day 18–21 post-infection may therefore indicate a “tipping point” in peripheral TNFα levels, where significant myositis breaches the threshold required to produce anorexia." (PMID 23349631, 2013). "Previous studies have also shown elevated muscle levels of numerous cytokines associated with type 1 inflammation, including CCL5, CXCL9, CXCL10, CXCL11, IFNG, and TNF in IBM patients compared to various myositis and non-myositis controls." (PMID 40034760, 2025). "IFN-α, another cytokine up-regulated in myositis muscle, induced Il15 and Il15ra mRNA and IL-15/IL-15Rα complex protein to the level similar to those induced by IFN-γ or TNF-α." (PMID 26417430, 2015). "More importantly, blockade of TNF-α with monoclonal antibodies has been shown to improve C protein-induced myositis (CIM) in mice, suggesting a probable role for autophagic pathways in myositis pathology." (PMID 23758833, 2013). "Indeed, it has been suggested that TNF-alpha may have a role in the pathogenesis of the myositis in the inflammatory myopathies and that a marked inflammatory response involving TNF-alpha may be directly responsible for damaging muscle fibres in myopathic conditions." (PMID 22505941, 2012). "The overexpression of T helper type 1 (Th1)-associated proinflammatory cytokines in the areas of inflammation such as TNF-α, IFN-γ, and IL-12 supported that Th1 might be the primary pathway for inflammation in myositis." (PMID 31429786, 2019). "To test the hypothesis that TNF-alpha is involved in such a condition, we used a rabbit muscle overuse model and investigated the presence of TNFR1 and TNFR2 in the myositis process." (PMID 29183282, 2017). "The use of a third anti-TNF-α drug, adalimumab, has not yet been reported in myositis treatment but has been helpful for interstitial pneumonitis associated with adult dermatomyositis, anti-synthetase syndrome, and orbital myositis." (PMID 28610606, 2017). "In our opinion, it can therefore not be excluded that TNF-alpha blocking can have negative effects in the reparation phase after the muscle damage/myositis." (PMID 29183282, 2017). "MRI showed excellent utility in detecting granulomatous myositis in patients without typical myositis features and anti-TNF monoclonal antibody therapy was efficacious in our refractory case." (PMID 27832822, 2016). "Probably these patients were affected by antisynthetase syndrome as baseline disease (in absence of myositis) and the onset of myositis (DM in one case and PM in four cases) was triggered by the initiation of TNF-α blocker." (PMID 24600322, 2014). "The TNF system has not been examined in any of these myositis models replicating the inflammatory myopathies seen in man." (PMID 22505941, 2012). "However, without further information, it is difficult to reach conclusions on the importance of TNF-alpha and the possible usefulness of TNF-blocking in muscle disorders, including in myositis." (PMID 22505941, 2012). "Expression of IL-1β and TNF-α was detected in perivascular infiltrating macrophages and microglia in the spinal cords of patients with HAM/TSP and in infiltrating macrophage in the muscle of patients with HTLV-I-related myositis." (PMID 22335964, 2012). "A digoxigenin-(DIG) hyperlabeled oligonucleotide probe (ssDNA) for detection of rabbit TNF-alpha mRNA was used on sections from myositis (4 specimens) and nonmyositis (1 specimen) groups (GD1001-DS custom designed; GeneDetect, New Zealand)." (PMID 22505941, 2012).
myositis (continued). "An animal model in which the importance of TNF-alpha for myositis development can be followed has previously been lacking." (PMID 22505941, 2012). "In contrast, another anti-TNFα drug, etanercept, does not appear to be as effective for myositis." (PMID 28610606, 2017). "In addition, TNF-α has been hypothesized to activate immune cells and induce MHC class I expression in the myositis muscle." (PMID 23758833, 2013). "In fact, muscle biopsies of myositis patients show a significantly increased expression of TLR-2, TLR-3, TLR-4, and TLR-9 in the skeletal muscle and infiltrating cells as well as the enhanced expression of cytokines such as IFN-γ, IL-4, IL-17, TNF-α, IL-6 and type 1 IFNs." (PMID 23758833, 2013). "However, TNF inhibition does not treat myositis and may even worsen certain aspects." (PMID 40861474, 2025). "As the myositis process also occurs in the nonexperimental side and as TNF receptors are confined to nerve fascicles bilaterally it can be asked whether TNF-alpha is involved in the spreading of the myositis process to the contralateral side via the nervous system." (PMID 29183282, 2017).